IL6 (interleukin 6)
Diseases named in the same sentence as IL6 in open-access papers (continued):
Sharing a sentence is not in itself a finding about the gene and the disease.
COVID-19 (continued). "Recent studies also showed that the level of IL-6 in severe cases was significantly higher than that in mild and moderate cases, but the levels of CD4+ T cells, CD8+ T cells and NK cells were decreased, indicating the immunosuppression in severe COVID-19 patients." (PMID 33329533, 2020). "However, there was a significant correlation between EBV viremia and interleukin-6 (IL-6) level (r = 0.621, p = 0.006) in COVID-19 patients, but not in non-COVID-19 patients (r = − 0.195, p = 0.438, Spearman’s rank-order correlation)." (PMID 33228750, 2020). "Taken together, consistent with previous research 2,5, the ESR, CRP, PT, IL6, lymphocyte count, GGT, Prealbumin and CD4 have important value in the diagnosis of COVID-19, and the decrease of GGT may be an important indicator for judging the intestinal dysfunction of patients." (PMID 32547309, 2020). "Contrary to this chronic disease, COVID-19 may be assimilated to an acute infection and thus, may not require an anti-IL6 effect as prolonged as in rheumatoid arthritis, which may explain how clinical efficacy was obtained so quickly in the present study." (PMID 33080877, 2020). "In the late stage of COVID-19, severe cases had extremely low CD4+ T cells and CD8+ T cells, but unusually high neutrophils [6.5 × 109/L (IQR, 4.8–9.6)], procalcitonin [0.27 ng/mL (IQR, 0.14–1.94)], C-reactive protein [66 mg/L (IQR, 25–114)] and an extremely high level of interleukin-6." (PMID 32983157, 2020). "Besides the anticoagulant effect of LMWH, nonanticoagulant properties such as the reduction in interleukin 6 release have been shown to improve the complex picture of coagulopathy in patients with COVID-19." (PMID 32677459, 2020). "IL-6 levels were not different between COVID-19 patients and HC." (PMID 32591408, 2020). "In addition, considering the pleiotropic effects of CAM on cytokines including IL-6 and its indirect antiviral effects, CAM might be worth a try for treating COVID-19." (PMID 33014130, 2020). "In addition, this study analyzed the transcriptome of bronchial epithelial cells and the serum cytokine and chemokine profiles of deceased COVID-19 patients, and confirmed an increase in inflammatory chemokines like IL-6, IL1RA, CCL2 and CCL8, suggesting immunologic misfiring in COVID-19." (PMID 32887790, 2020). "While some studies report inflammatory monocytes as the source of IL-69,42,43, our results suggest that immature neutrophils could also be a non-negligible source of IL-6 during COVID-19-induced cytokine storm." (PMID 33067472, 2020). "Besides, IL-6 was shown to be elevated to over 1000 pg/ml in patients with sepsis, even higher than half of the critically ill COVID-19 patients in our cohort, but acute lung injury was not more common in sepsis than COVID-19." (PMID 33121497, 2020). "However, the role of IL-6 as an independent predictor of severity and mortality in hospitalized COVID-19 patients has not been validated." (PMID 32765283, 2020). "However, both positive and negative results have been reported regarding the use IL-6 blockers to treat COVID-19." (PMID 33003552, 2020). "Notably, cytokines such as TNF-α, IL-1β, IL-6, IFN-γ, and IL-10 not only amplify the production of additional cytokines—including themselves—but also play critical roles in regulating immune cell differentiation and function, thereby exacerbating immune dysregulation in severe COVID-19." (PMID 41596316, 2026). "Compared to non-severe adult COVID-19 patients, severe adult patients exhibited dramatically increased secretion of Th1 proinflammatory cytokines, in particular, IL-1β (40.79 vs. 207.84), IL-6 (112.90 vs. 304.15), and IL-8 (1454.66 vs. 2829.79, p = 0.001) in BALF." (PMID 39967737, 2025). "Additionally, elevated IL-6 increases biochemical indicators such as CK-MB and GLU and decreases Mg, suggesting that both COVID-19 and psychosis affect multiple organ systems and may be related to cardiac injury, glycometabolic disorders, and electrolyte imbalance." (PMID 40292283, 2025).
COVID-19 (continued). "Consequently, clinical guidelines developed for the management of sepsis prior to the emergence of COVID-19 may not be fully applicable to critically ill COVID-19 patients (e.g., the use of glucocorticoids or IL-6 monoclonal antibody such as tocilizumab)." (PMID 41270075, 2025). "Interestingly, PCT was also tightly linked to IL6 and TNF superfamily members, underscoring that elevated PCT in COVID-19 is not solely attributable to bacterial coinfection but may instead reflect a state of profound systemic inflammation." (PMID 41373577, 2025). "Therefore, IL-6 was evaluated in this study in COVID-19-positive and negative patients over time." (PMID 39582872, 2024). "The absence of significant difference in IL-6 between individuals with and without post-COVID-19 symptoms contrasts the results of a recent meta-analysis, which showed an elevation of IL-6 in individuals presenting with post-COVID-19 symptoms compared to healthy individuals." (PMID 39056056, 2024). "Similarly, our data indicated that hypertension APs not only had higher WBCs, neutrophils, basophils, IL-6, and CRP levels but also had lower virus-specific IgM levels than non-hypertension APs, which further immunologically confirms that hypertension had adverse effects on COVID-19 APs." (PMID 38666774, 2024). "Similarly, increased levels of interleukin-1 (IL-1), IL-6, IL-7, IL-10, tumor necrosis factor-alpha (TNF-α), and reduced expression of interferons (IFNs) have been associated with negative outcomes in individuals with COVID-19." (PMID 38601541, 2024). "Furthermore, while systemic increases in IL-1β, IL-6, TNF-α, and IFN-γ have traditionally been viewed as immunopathological hallmarks of acute COVID-19, most of these cytokines, along with several markers of brain injuries, have recently emerged as potential biochemical indicators of long COVID-19." (PMID 38338174, 2024). "There have been no exact or fixed treatment recommendations for COVID-19 have been issued to date, but recent studies have demonstrated that cytokine blockades that specifically target cytokines, such as interleukin IL-1 and IL-6, offer optimistic therapeutic promise for COVID-19." (PMID 37742314, 2024). "Therapy with anti-mIL-6R/sIL-6R mAbs (e.g., tocilizumab and sarilumab) may help to suppress the cytokine storm in severe cases of COVID-19; however, the consistent message of related studies is that there is no broad-based benefit of IL-6 blockade in COVID-19 patients." (PMID 37109231, 2023). "Sensitivity analysis without adjusting IL-6 levels for age and BMI levels at the time of plasma collection, produced almost identical results to the main analysis: β = 0.321 ± 0.115, p = 0.005; and β = − 0.061 ± 0.180, p = 0.774 for COVID-19-negative and COVID-19-positive participants, respectively." (PMID 36995412, 2023). "Consequently, crucial inflammatory markers in COVID-19, such as interleukin-6 and ferritin, could not be consistently determined in the ED due to a lack of reagents." (PMID 37888108, 2023). "However, in older COVID-19 patients more and stronger correlations could be detected with hs-CRP (all p < 0.01): IL8 (r = 0.548), MCP3 (r = 0.720), CXCL10 (r = 0.460), CCL23 (r = 0.577) and IL6 (r = 0.706)." (PMID 37832397, 2023). "Thus, it is possible that proinflammatory cytokines such as IL-6 and chemokines as well as complement activation with subsequent C5a and C3a release during SARS-CoV-2 infections may result in MC degranulation and development of urticaria in COVID-19 patients." (PMID 37515272, 2023). "Therefore, IL-6 can be considered a useful biomarker in diagnosis infection and cardiovascular diseases, different kinds of cancer, and other diseases such as lung fibrosis, chronic intestinal inflammation, acute kidney injury (AKI), chronic kidney disease (CKD) and, recently, COVID-19." (PMID 37754132, 2023).
COVID-19 (continued). "Finally, another meta-analysis of 22 case-control observational studies has found that IL-6 was higher in patients with LC compared with healthy individuals and those without post-acute sequelae of COVID-19 but lower than in patients during the acute phase of COVID-19." (PMID 37445634, 2023). "Consequently, several drugs/compounds targeting IL-1β or IL-6 have been evaluated in several phase 3 clinical trials each (NCT04372186, NCT04409262, NCT04678739, NCT04364009, NCT04443881 and NCT04324021) as therapeutic option of SARS-CoV-2 infection to treat or prevent severe COVID-19 evaluated." (PMID 36941580, 2023). "As already reported in other studies, we also observed that COVID-19 patients had significantly highly expressed non-specific inflammatory markers such as hs-CRP levels in the plasma that might also induce the production of IL-6." (PMID 37832397, 2023). "Cohort A consisted of patients with COVID-19 with a negative CT scan for pulmonary thrombosis and elevated thromboinflammatory markers (D-dimer > 10,000 ng/mL or 5,000 < D-dimer < 10,000 ng/mL and one of: C-reactive Protein > 100 mg/dL, IL-6 > 6 pg/mL, or ferritin > 900 ng/L)." (PMID 36873865, 2023). "Moreover, levels of CRP, IL-6, IL-8, IL-10, tumor necrosis factor (TNF)-α and IL-2R showed a positive correlation with high-sensitivity cardiac troponin I, consistent with the contribution of the inflammatory response to cardiac injury present in COVID-19 patients." (PMID 37168848, 2023). "Finally, we identified certain parameters such as Interleukin (IL)-6 concentration, C reactive protein (CRP) level and platelet count that allowed to discriminate between death and survival in patients hospitalized with severe COVID-19 only during the first wave." (PMID 36817433, 2023). "Similarly, when characterising the Th1/Th2/Th17 cytokine profiles among the different stages of COVID-19 infection, it was found that most of them were elevated in patients with COVID-19 but were not statistically significant, except for pro-inflammatory IL-6 or Th1 cytokines." (PMID 37110363, 2023). "In COVID-19, a retrospective analysis of tocilizumab therapy in relation to baseline IL-6 levels showed a significant reduction in mortality (from 36% to 16%) in patients with baseline IL-6 levels above 30 pg/ml but no reduction in mortality in IL-6 below 30 pg/ml." (PMID 37650680, 2023). "Other non-specific biomarkers of COVID-19, such as the presence of neutrophilia, thrombocytopenia, hypoalbuminemia, elevation of liver enzymes and creatinine, as well as inflammatory markers, such as C-reactive protein (CRP) and interleukin 6 (IL-6), were also associated with a worse prognosis." (PMID 37109370, 2023). "However, it has not been reported whether IL-6 inflammation persists in tissues in the later stages of severe COVID-19 when viral titers diminish." (PMID 36497139, 2022). "As both IFN-α and IL-6 are PAMP-triggered inflammatory cytokines, the presence of SARS-CoV-2 RNA in the bloodstream may reflect a heightened immune exposure to PAMPs, adding to the already amplified pro-inflammatory signature featuring acutely ill COVID-19 patients." (PMID 36385627, 2022). "However, the inflammatory response in COVID-19 still shares some common signatures with the inflammatory response in LPS-induced RAW264.7 cells, among which the most typical are TLR4, NF-κB, and other signaling pathways and their corresponding cytokines (including IL-6, TNF, IL-1β, etc.)." (PMID 35669076, 2022). "This could indicate an early role for IL-6 in COVID-19 pathogenesis and be consistent with the clinical observation that IL-6 blockade does not shorten the duration of IMV among patients receiving IMV at initiation but does reduce risk of progression to IMV or death when initiated earlier." (PMID 34710339, 2022).
COVID-19 (continued). "However, in the COVID-19 context, the greater availability of tryptophan will allow for its metabolism through the kynurenine pathway, whose metabolites will induce the expression of the pro-inflammatory IL-1β, IL-10, TNF-α, IL-6 by AHR, further increasing the local and systemic inflammation." (PMID 36293182, 2022). "Indeed, diabetic patients have significantly higher serum inflammatory biomarkers including IL-6, C-reactive protein (CRP), D-dimer, serum ferritin and coagulation indices, resulting in a higher chance of an inflammatory storm and eventually worsening the outcome of COVID-19." (PMID 36143101, 2022). "Interestingly, IL-6 and IL-10 are increased among severe and non-survivor COVID-19 cases." (PMID 35572964, 2022). "Even though the pathophysiology of COVID-19 has not yet been fully understood, critically ill patients have high levels of cytokines, particularly interleukin-6 (IL-6), suggesting that hyperinflammation may contribute to morbidity and mortality in this disease." (PMID 36326337, 2022). "This could explain the hematological findings in COVID-19 severe cases including leukocytosis, lymphopenia, thrombocytopenia, neutrophilia, elevations in erythrocyte sedimentation rate, C-reactive protein (CRP), IL-6, fibrinogen, ferritin, lactate dehydrogenase, and D-dimer." (PMID 35408447, 2022). "However, IL-6 blockade may not be effective in some severe COVID-19, and largely depended on many factors including baseline IL-6 levels, PaO2/FIO2, requirement of HFO or NIV, levels of CRP, ferritin, D-dimer, and LDH." (PMID 35632823, 2022). "Conversely, some investigators have hypothesized that new onset AF might induce an increase in IL-6 serum levels leading to pulmonary vascular dysfunction and cardiac immune response in subjects with respiratory distress and hypoxemia due to COVID-19, but confirmatory studies are lacking." (PMID 35454369, 2022). "Similarly, activation of COX2 and HIF-1α in COVID-19 has been shown to upregulate the antiapoptotic antiproliferative microenvironment (BCL2, BNIP3) and M1 immune system {nuclear factor kappa B (NFKB), Egl-9 family hypoxia inducible factor 3 (EGLN3), CXCL8, TNF-α, and IL-6 }." (PMID 36671699, 2022). "Therefore, this study aimed to investigate the serum testosterone, inhibin B, intrleukin-6 (IL-6) and tumor necrosis factor-alpha (TNF-a) levels in different age groups of Jordanian males with SARS-CoV2 infection and to evaluate the correlation of these markers in male patients with COVID-19." (PMID 36381078, 2022). "Besides IL-6, IL-1 and TNF-α could be a predictor of cytokine storm and COVID-19 progression." (PMID 36111104, 2022). "First, we studied the circulating levels of IL-1α, IL-1β, IL-18, IL-15, IL-12p40, IL-12p70, IL-6, IL-27, IL-1Ra, IL-1RI, IL-1RII, IL-6R and sgp130, which are innate proinflammatory cytokines, and their receptors in survivors and non-survivors of severe COVID-19 and healthy controls." (PMID 36142255, 2022). "However, we could not conclude that IL-6 mediated inflammation may continue in the tissues during the latter stages of severe COVID-19, when the viral load ends." (PMID 36298704, 2022). "However, plasma levels of IL-6 were shown to be a reliable negative prognostic index, demonstrating a directly proportional and significant correlation with the severity of the clinical picture of COVID-19." (PMID 33983525, 2022). "In contrast, another single-center study reported negative results for removing circulating cytokines and inflammatory chemokines in non-AKI patients with severe COVID-19, which might be attributed to the relatively lower concentration of IL-6 in COVID-19 patients than in patients with septic shock." (PMID 36431196, 2022). "Expression of receptors for IL-6 (IL-6R and IL6ST) was observed across all cell types, indicating that a feedback loop between IL-6 responsiveness and NOTCH signaling remains a possible feature which might contribute to the inflammatory response during COVID-19." (PMID 35992174, 2022).
COVID-19 (continued). "Similarly, the concentrations of IL-6, IL-8 and TNFα correlated with the surface expression of CD11b and CD66b in the pooled analysis, whereas only IL-8 and TNFα (but not IL-6) correlated with the percentage of CD49d+ neutrophils when the COVID-19 and Control groups were combined for analysis." (PMID 36466824, 2022). "In animal cell lines, C. sativa has been verified to reduce the expression levels of IL-6, IL-8, C-C motif chemokine ligands (CCLs) 2 and 7, and ACE2, suggesting that it may be a valuable contributor to existing anti-inflammatory regimens for the management of COVID-19." (PMID 34066983, 2021). "Since severe COVID-19 patients show high expression of TLR4 in PBMCs, we can speculate that the activation of this receptor by LPS derived from the gut microbiota of elderly, diabetic, and hypertensive individuals would also potentiate the production of IL-6 induced by SARS-CoV-2." (PMID 34458281, 2021). "In addition to IL-6, HMGB1 might also be a potential therapeutic target in severe COVID-19." (PMID 33939645, 2021). "Here we systemically analyzed the clinical characteristics of pregnant and non-pregnant female COVID-19 patients who were hospitalized during the same period and found that pregnant patients developed marked lymphopenia and higher inflammation evident by higher C-reactive protein and IL-6." (PMID 34326311, 2021). "Indeed, severe COVID-19 cases display higher prevalence and levels of EBV viremia compared with non-COVID critically ill subjects; the virus’s DNA titers and anti-EBNA1 IgM levels correlate with increased inflammatory markers (C-reactive Protein, IL-6), disease severity, and prognosis." (PMID 34646278, 2021). "Notably, the concentration of IL-6 was significantly higher in non-survivors than in survivors (p<0.01), suggesting that IL-6 has predictive value for mortality in COVID-19 patients." (PMID 34123873, 2021). "In addition, IL-6 levels are significantly higher in COVID-19 nonsurvivors than in survivors." (PMID 34567235, 2021). "This is one of the few reported cases of COVID-19-related psychosis in a patient without a personal or family history; moreover, this description contains important data regarding elevated IL-6, which may prove to be a key factor in the induction of new psychotic symptoms." (PMID 34721104, 2021). "In fact, brain lesions associated to COVID-19 reflect both vascular and demyelinating etiologies and are mainly imputable to the intense immune activation with massive neurotoxic cytokines production (in particular, IL1-beta and IL6), rather than a direct infectious cytopathic effect." (PMID 34646278, 2021). "Additionally, the concentrations of IL-1β (1,236.5 ± 398.1; p = 0.0105), IL-6 (1,408.9 ± 490.3; p = 0.0198), and IL-8 (1,443.4 ± 195.8; p = 0.0012) were significantly upregulated in the critical COVID-19 non-survival group compared to the critical COVID-19 survival group." (PMID 34276659, 2021). "During COVID-19, it has been well reported that the condition of inpatients could be worsening quickly after the cytokine storm: For this reason, the downregulation of IFN-γ and IL-6 inflammatory responses has been reported as negative prognostic markers in critically ill COVID-19 patients." (PMID 33803015, 2021). "First, some inflammatory markers (such as ferritin, TNF-α, and IL-6) that were confirmed to be elevated during cytokine storm in patients with severe COVID-19 may not be available in most grassroots hospitals or laboratories in developing countries and are mainly used for research purposes." (PMID 34900028, 2021). "This pilot trial shows that the addition of high-dose (24 g per day for 7 days) intravenous vitamin C to the standard-of-care treatment for severe COVID-19 did not affect ventilation-free days, but may provide a potential signal of benefit in oxygenation and IL-6." (PMID 33420963, 2021).